MDM4 (MDM4 regulator of p53)
Diseases named in the same sentence as MDM4 in open-access papers (continued):
Sharing a sentence is not in itself a finding about the gene and the disease.
cancer (continued). "Additional kinases that phosphorylate MDM4 under defined conditions are elaborated in this section in the context of health and cancer risk." (PMID 30689920, 2019). "Recent data from the Collaborative Oncological Gene-environment Study (COGS) identified SNP34091 in the 3′ UTR of the human MDM4 gene, as a cancer risk locus in hormonally mediated cancers." (PMID 31547268, 2019). "Allele C of rs4245739 can cause decreased expression of MDM4 mRNA46, leading to a protective effect against cancer." (PMID 30038284, 2018). "Association between genetic variations in this region of MDM4 gene and cancers had been investigated in previous studies." (PMID 27462918, 2017). "The occurrence of the C minor allele (SNP rs4245739 A>C) in the 3'-UTR of MDM4 has been shown to decrease the risk of cancer, and delay the progression of metastasis and cancer-related death." (PMID 28381629, 2017). "Accordingly, it has been recently proposed that the mechanism that underlies MDM4 upregulation in different cancer cells depends on a specific alternative splicing switch promoting exon 6 inclusion." (PMID 28230750, 2017). "To date, no meta-analysis has been conducted to comprehensively investigate the association of MDM4 rs4245739 A > C with overall cancer risk." (PMID 27687591, 2016). "We therefore performed the PRISMA- compliant meta-analysis of the accumulated information and evaluated the associations of MDM4 polymorphisms with cancer susceptibility." (PMID 27738340, 2016). "To overcome these limitations, we performed a meta-analysis of the contradictory results from these relevant studies to clarify the possible associations between MDM4 gene polymorphisms and cancer risk." (PMID 27742919, 2016). "The results showed that the MDM4 rs4245739 polymorphism is associated with a significantly decreased risk of cancer." (PMID 27738340, 2016). "To address the controversy regarding this association, we performed the current meta-analysis to precisely define the effect of MDM4 rs4245739 A > C polymorphism on overall cancer risk." (PMID 27687591, 2016). "The aim of this meta-analysis was to evaluate the associations between MDM4 gene polymorphisms and cancer risk." (PMID 27742919, 2016). "In conclusion, our meta-analysis revealed that MDM4 gene rs4245739 A > C polymorphism was associated with a reduction in overall cancer susceptibility." (PMID 27687591, 2016). "Currently, many studies have investigated the associations between MDM4 gene polymorphisms and cancer risk." (PMID 27742919, 2016). "In the present meta-analysis comprising 69477 subjects from 15 studies, we completed the first comprehensive evaluation of the association between MDM4 gene rs4245739 A > C polymorphism and overall cancer risk." (PMID 27687591, 2016). "Considerable studies have investigated the associations between MDM4 gene polymorphisms and cancer risk recently, but with contradictory results." (PMID 27742919, 2016). "Although this is the first meta-analysis investigating the association between MDM4 gene rs4245739 A > C polymorphism and overall cancer risk, some limitations should be discussed." (PMID 27687591, 2016). "In conclusion, this meta-analysis indicates that rs4245739 polymorphism of MDM4 gene plays important roles in cancer pathogenesis, especially among Asian populations." (PMID 27742919, 2016).
cancer (continued). "Prompted by the important role of MDM4 in the development of cancer, we have conducted the first comprehensive meta-analysis of the relationships between MDM4 polymorphisms and the risk of cancer." (PMID 27738340, 2016). "Previous molecular epidemiology studies suggest that genetic variations in MDM4 gene are associated with risk of various types of cancer." (PMID 27687591, 2016). "Numerous previous studies have investigated the association between MDM4 gene polymorphisms and cancer susceptibility." (PMID 27687591, 2016). "To provide a comprehensive and reliable conclusion, we conducted a meta-analysis to assess the associations between MDM4 gene polymorphisms and cancer risk." (PMID 27742919, 2016). "In the last decades, several single nucleotide polymorphisms in the MDM2 as well as the MDM4 loci have been associated with elevated or reduced cancer risk, although data are at variance." (PMID 26867771, 2016). "Among the many MDM4 polymorphisms, a common genetic variant rs4245739 A > C has been widely investigated for its association with cancer susceptibility." (PMID 27687591, 2016). "In short, several SNPs in the MDM4 have been associated with elevated or reduced cancer risk, but data are at variance." (PMID 27738340, 2016). "In summary, this meta-analysis has demonstrated that the MDM4 rs4542739 polymorphism was associated with decreased cancer risk, especially in Asian populations." (PMID 27738340, 2016). "Ultimately, 17 articles focusing on the association between MDM4 polymorphisms and cancer risk were identified." (PMID 27738340, 2016). "The pooled results indicate that the MDM4 rs4245739 A > C polymorphism was significantly associated with decreased overall cancer risk, which was consistent with the results of our genotype-based mRNA expression analysis." (PMID 27687591, 2016). "In this study, we assessed the impact of MDM4 SNP34091 status on the risk of cancer of the breast, lung, prostate, and colon in a large population‐based cohort of Caucasian descent." (PMID 26471763, 2015). "First, mRNA from the C allele but not the majority A allele of rs4245739 (a SNP in the 3′ UTR of MDM4) has been demonstrated to be decreased by miR-191, and hence the A allele is associated with high-grade carcinomas and higher expression of MDM4." (PMID 22870278, 2012). "These splice variants have mostly been identified in the cancer field and there appears to be little, if anything in the literature about the roles of these potential splice variants/cleavage products of Mdm4/X in embryonic development." (PMID 19450442, 2009). "Beyond cancer, MDM4 has been implicated in other pathological states." (PMID 40813720, 2025). "First, we explored the diagnostic value of MDM4 for the malignant cancers." (PMID 38281029, 2024). "Two recent experiments showed that the change in the MDM4 3′-UTR may contribute to a low risk of different cancers." (PMID 36755123, 2023). "Gene variations in MDM4 were reported to be associated with risk to cancer." (PMID 36831624, 2023).
cancer (continued). "In addition, several of the single nucleotide polymorphisms identified in MDM4 have been linked to various cancers and their aggressiveness." (PMID 36980876, 2023). "Single nucleotide polymorphisms (SNPs) in MDM2 and MDM4 have been associated with various cancers." (PMID 33669778, 2021). "Although MDM4 is primarily known for its clinical relevance in cancer biology, our study shows that a germline missense MDM4 mutation may cause features suggestive of DC." (PMID 32300648, 2020). "Thus, we are unable to consider our results contradictory to those who reported associations of the variant genotypes of MDM4 rs4245739 with a reduced risk of cancer." (PMID 32492903, 2020). "A number of SNPs in MDM4 have been linked with altered cancer susceptibility." (PMID 30689920, 2019). "The pooled results revealed that the MDM4 rs4245739C allele is associated with a decreased cancer risk in the heterozygous (AC vs. AA: OR = 0.82, 95% CI = 0.73−0.93), dominant (AC/CC vs. AA: OR = 0.82, 95% CI = 0.72−0.93), and allele contrast models (C vs. A: OR = 0.84, 95% CI = 0.76−0.94)." (PMID 27687591, 2016). "The somewhat variable results regarding MDM4 rs4245739 and cancer risk may also be explained by yet unknown functional SNP (s) that are in linkage disequilibrium with rs4245739." (PMID 27738340, 2016). "All above studies indicated that MDM4 gene may be significantly associated with cancer susceptibility." (PMID 27742919, 2016). "We found that the MDM4 rs4245739C carriers had a significantly decreased overall cancer risk under the heterozygous [AC vs. AA: odds ratio (OR) = 0.82, 95% CI = 0.73–0.93], dominant (AC + CC vs. AA: OR = 0.82, 95% CI = 0.72–0.93), and allele contrast models (C vs. A: OR = 0.84, 95% CI = 0.76–0.94)." (PMID 27687591, 2016). "Molecular epidemiological research suggests that genetic variations in MDM4 gene may be associated with the cancer risk." (PMID 27738340, 2016). "Molecular epidemiological research suggests that mouse double minute 4 (MDM4) polymorphisms may be associated with cancer susceptibility, but results remain controversial." (PMID 27738340, 2016). "In light of these findings, we hypothesize that MDM4 may play pivotal roles in the pathogenesis of cancer, and that MDM4 is a candidate susceptibility gene for cancer." (PMID 27742919, 2016). "In conclusion, our analyses indicated that rs4245739 polymorphism in the MDM4 gene may play an important role in the etiology of cancer." (PMID 27742919, 2016). "This is the first meta-analysis to evaluate whether SNPs in the MDM4 gene are associated with cancer risk." (PMID 27738340, 2016). "Because rs4245739 C-to-A change could destroy RNA::RNA interaction between miR-191 and MDM4 mRNA and increased MDM4 expression in cancer cells, we studied if there is an allele-specific effect of rs4245739 SNP on MDM4 expression in esophagus tissues." (PMID 23724042, 2013).
cancer (continued). "Thus the MDM4 rs4245739 A > C polymorphism appears to be associated with decreased cancer risk." (PMID 27687591, 2016). "Ribosomal protein-mediated control of MDM2 and MDM4 has implications for how cancer cells respond to chemotherapy." (PMID 40427096, 2025). "Collectively, these studies establish RPL22 as a novel regulator of MDM4 with possible future implications for cancer prognosis and therapy." (PMID 40427096, 2025). "In brief, our studies shows that MDM4 is emerging as an attractive therapeutic target for a variety of malignant neoplasms." (PMID 38281029, 2024). "In this article, we analyzed the expression levels of MDM4 in pan-cancer through multiple databases." (PMID 38281029, 2024). "Although extensive research has been carried out on the carcinogenic effects of MDM4, the role of MDM4 in pan-cancer is still elusive." (PMID 38281029, 2024).
cancer (continued). "In previous studies, we discovered a small molecule, (10-methylanthracen-9-yl)methyl carbamimidothioate (XI-011), which effectively inhibits MDM4 expression in cancer cells." (PMID 38792257, 2024). "Understanding the regulatory mechanism of MDM4 protein levels in cancer is of therapeutic significance." (PMID 38462618, 2024). "These should be considered as inflammatory cell infiltration rather than anti-tumor immune response because the ESTIMATEScore has a linear decline in diverse kind malignant tumors with increasing MDM4 expression." (PMID 38281029, 2024). "For example, we identified two pan-cancer differentially expressed RNAPII-bound regions on enhancers located 10 kb upstream of the MDM4 gene." (PMID 37868033, 2023). "We identified cancer genes recurrently overexpressed across the cohort, e.g., MDM4 in six and CDC73 and TPR in five tumors, respectively." (PMID 36230794, 2022). "Many therapeutics, which are inhibitors of Mdm2 or Mdm4, have entered clinical trials but have yet to be proven to be safe and effective in cancer treatment, such as milademetan, RG7112, RG7388, CGM097, HDM201, and ALRN-6924." (PMID 36362074, 2022). "This study provides a prototype structure for developing MDM4/FTH1 dual-targeting inhibitors as potential cancer therapeutics." (PMID 36431769, 2022).